CTDSP1 (CTD small phosphatase 1)
Description:
Preferentially catalyzes the dephosphorylation of 'Ser-5' within the tandem 7 residue repeats in the C-terminal domain (CTD) of the largest RNA polymerase II subunit POLR2A. Negatively regulates RNA polymerase II transcription, possibly by controlling the transition from initiation/capping to processive transcript elongation. Recruited by REST to neuronal genes that contain RE-1 elements, leading to neuronal gene silencing in non-neuronal cells.
Synonyms: NLI-IF; SCP1; NIF3; NLIIF
Tractability: Small molecule: a structure with a bound ligand is known; it belongs to a druggable protein family. PROTAC: ubiquitination databases record sites on it; its protein half-life has been measured; a small molecule that binds it is known.
Target class: Protein Phosphatase; Phosphatase; Serine/threonine protein phosphatase; Enzyme
Gene: Protein-coding gene on chromosome 2 (218,397,136 to 218,405,942, forward strand). Ensembl gene ENSG00000144579.
Subcellular location: Nucleus
Subcellular location (Human Protein Atlas): Nucleoplasm
Gene Ontology:
Molecular function: protein binding; protein serine/threonine phosphatase activity; RNA polymerase II CTD heptapeptide repeat phosphatase activity; phosphatase activity
Biological process: protein dephosphorylation; regulation of transcription by RNA polymerase II
Cellular component: extracellular exosome; nucleoplasm; nucleus
Genetic constraint (gnomAD): Loss-of-function variants: 15 observed, 33.66 expected, observed/expected ratio (o/e) 0.45, 90% interval 0.3 to 0.69. The upper end of that interval is the gene's LOEUF score, 0.69, which puts it in group 2 of 6, group 1 being the genes least tolerant of losing a copy. Missense variants: 294 observed, 359.63 expected, observed/expected ratio (o/e) 0.82, 90% interval 0.74 to 0.9. Synonymous variants: 185 observed, 150.57 expected, observed/expected ratio (o/e) 1.23, 90% interval 1.09 to 1.39.
Homologues: Orthologues: chimpanzee CTDSP1 (100% identical), mouse Ctdsp1 (99% identical), pig CTDSP1 (98% identical), dog CTDSP1 (93% identical), rat Ctdsp1 (92% identical), guinea pig CTDSP1 (92% identical), tropical clawed frog ctdsp1 (75% identical), zebrafish ctdsp1 (75% identical), Drosophila melanogaster hzg (61% identical), Caenorhabditis elegans scpl-1 (60% identical). Paralogues in human: CTDSPL (69% identical), CTDSP2 (62% identical), CTDSPL2 (38% identical), CTDNEP1 (35% identical), TIMM50 (24% identical).
Diseases named in the same sentence as CTDSP1 in open-access papers:
CTDSP1 is named in the same sentence as 23 diseases in open-access papers, as found by Europe PMC text mining. Sharing a sentence is not in itself a finding about the gene and the disease. The quoted sentences say what the papers report.
breast carcinoma (3 papers, 2019 to 2022). "Oncogenic genes like FAM83D, CTDSP1, and SAPCD2 were downregulated in all three cells, and tumor suppressor genes (TSGs) like ZNF292, ANKRD12, NKAPL, and CCL21 were upregulated in all three breast cancer cells upon curcumin treatment." (PMID 34981672, 2022).
colorectal cancer (3 papers, 2020 to 2021). A primary or metastatic malignant neoplasm that affects the colon or rectum. "Carboxy-Terminal Domain RNA Polymerase II Polypeptide A Small Phosphatase 1 (CTDSP1) is related to the drug resistance of colorectal cancers." (PMID 34408975, 2021). "Furthermore, rabeprazole has been reported to regulate DNA-PKcs dependent topoisomerase I degradation and irinotecan drug resistance in colorectal cancer through CTD small phosphatase 1 (CTDSP1)." (PMID 34266494, 2021).
hepatocellular carcinoma (2 papers, 2013 to 2019). A malignant tumor that arises from hepatocytes. "CTDSP1/2/L and miR-26a/b are co-expressed in concert with cell cycle phases in hepatocellular carcinoma." (PMID 31774910, 2019). "Gain- and loss-of-function studies showed that miR-26b and its host genes CTDSP1/2/L cooperate to block G1/S-phase progression by activating pRb protein in hepatocellular carcinoma." (PMID 23374284, 2013).
colon cancer (1 paper, 2020). "The purpose of this study was to confirm the effects of rabeprazole on CTDSP1 activity and its impact on irinotecan-based therapy in colon cancer." (PMID 32764831, 2020).
ischemia (1 paper, 2023). A hypoperfusion of the BLOOD through an organ or tissue caused by a PATHOLOGIC CONSTRICTION or obstruction of its BLOOD VESSELS, or an absence of BLOOD CIRCULATION. "After we found that the expression of miR-124-3p and CTDSP1 was altered under ischemia, we wanted to explore whether ELA could regulate miR-124-3p and downstream signaling molecules by activating the APJ receptor." (PMID 37106272, 2023).
kidney cancer (1 paper, 2019). Primary or metastatic malignant neoplasm involving the kidney. "Another member of the SCP subfamily, CTDSP1, suppressed proliferation, migration, and invasion of kidney cancer cells in vivo." (PMID 31774910, 2019).
kidney tumors (1 paper, 2023). "CTDSPL inactivation in kidney tumors may be mediated by mechanisms different from CTDSP1 and CTDSP2." (PMID 37629167, 2023).
lymph node metastases (1 paper, 2019). "In addition, we showed a clear difference of the CTDSP1, CTDSPL and RB1 relative mRNA levels in ADC with and without lymph node metastases, but not in SCC (P≤0.05)." (PMID 31774910, 2019).
lymphoma (1 paper, 2011). A malignant (clonal) proliferation of B- lymphocytes or T- lymphocytes which involves the lymph nodes, bone marrow and/or extranodal sites. "Myc was previously reported to regulate the expression of miRNAs, including miR-26a and miR-26b in P493 lymphoma cells, by direct binding to their host Pol II gene promoters (CTDSPL, CTDSP2, CTDSP1)." (PMID 21941025, 2011).
mesothelioma (1 paper, 2023). A usually malignant and aggressive neoplasm of the mesothelium which is often associated with exposure to asbestos. "However, according to TCGA data, somatic deletions only in the CTDSP1 gene are a frequent (up to 20% of samples of some cancers) driver event (GISTIC algorithm) in a variety of cancers, including kidney, lung, bladder, ovarian, breast, mesothelioma and other tumors." (PMID 37629167, 2023).
non-small cell lung carcinoma (1 paper, 2023). A group of at least three distinct histological types of lung cancer, including non-small cell squamous cell carcinoma, adenocarcinoma, and large cell carcinoma. "Recently, we demonstrated that CTDSP1, 2, and L inhibit the growth of A549 cells, a non-small-cell lung cancer cell line." (PMID 37629167, 2023).
pancreatic cancer (1 paper, 2015). "Furthermore, a study in pancreatic cancer reported a trend towards improved survival in patients with autoantibodies to the carboxy-terminal domain phosphatase CTDSP1." (PMID 25875936, 2015).
prostate carcinoma (1 paper, 2011). A carcinoma that arises from epithelial cells of the prostate gland. "We found a significant enrichment of MYC at the promoters of CTDSPL, CTDSP2 and CTDSP1 in both prostate cancer cell lines." (PMID 21941025, 2011).
tumor (7 papers, 2014 to 2025). "Earlier it was shown that CTDSP1 inhibits breast cancer cell migration and invasion and suppresses tumor properties of liver carcinoma, osteosarcoma, and uveal melanoma." (PMID 37629167, 2023). "In summary, CTDSP1 can be a tumor suppressor through inhibiting cancer cell migration and invasion by the dephosphorylation of TWIST and AKT." (PMID 32397221, 2020). "Many pieces of research have focused on the C-terminal activity of CTDSP1, but the understanding of N-terminal residues of CTDSP1 is evolving, with new activities identified in impeding tumor growth, invasion, and metastasis." (PMID 32397221, 2020). "For the first time we confirmed tumor suppressor properties of all three phosphatases, CTDSP1/2/L, in the A549 lung ADC cell line in vitro." (PMID 31774910, 2019). "Additionally, the functionality of CTDSP2 and CTDSPL, such as their catalytic activity against RNAP II CTD peptide and their tumor-suppressing role, also overlaps with that of CTDSP1." (PMID 32397221, 2020). "The direct interaction of AKT and CTDSP1 could negatively modulate angiogenesis by tumor growth suppression through dephosphorylation of Ser473." (PMID 32397221, 2020). "In addition, tumor suppressive activity of CTDSP1/2/L appears to be mediated through dephosphorylation of at least three serine residues of Rb (Ser807/811, Ser780, and Ser795 for each protein) in vitro." (PMID 31774910, 2019). "Recently, some studies demonstrated that CTDSP1 inhibited the proliferation, migration and invasion of cancer cells by inhibiting the dephosphorylation of TWIST and AKT, suggesting a tumor suppressor role of CTDSP1." (PMID 36452459, 2022). "Altogether, these data suggest tumor suppressor activity of CTDSPL, CTDSP1, and CTDSP2 genes in different types of cancer." (PMID 31774910, 2019). "In ccRCC cell lines 786-O and A-498, the ectopic expression of CTDSP1 suppressed proliferation, migration, and invasion of tumor cells in vitro and in vivo (no data regarding CTDSP2 and L)." (PMID 37629167, 2023). "Our data confirmed that CTDSP1 and CTDSPL (but not CTDSP2) exerts tumor suppressive activity in ccRCC." (PMID 37629167, 2023). "Furthermore, unlike CTDSP1/2/L proteins, CTDSPL2 has not been previously reported to act on pRb, a main tumor suppressor target common to the other 3 members of the family." (PMID 28915671, 2017).
cancer (5 papers, 2019 to 2023). A tumor composed of atypical neoplastic, often pleomorphic cells that invade other tissues. "Hence, here we are concentrating on how CTDSP1 is implicated in different cancer-related mechanisms and binding partners, as one of the new drug targets." (PMID 32397221, 2020). "In this work, we focused on the study of phosphatases CTDSP1, 2, and L. Their involvement in carcinogenesis was demonstrated for various cancers." (PMID 37629167, 2023). "Recent findings have denoted that negative regulation of CTDSP1 results in suppression of cancer invasion in neuroglioma cells." (PMID 32397221, 2020). "Apart from these known functionalities, a recent study related to cancer invasion exhibited the exciting results that CTDSP1 dephosphorylates Twist-related protein (TWIST) and regulates cancer cell migration." (PMID 32397221, 2020). "Additionally, no other similar phosphatases were able to constitute this reaction with the same efficiency, and the inverse concentration of TWIST1 and CTDSP1 has been observed in several cancer cell lines." (PMID 32397221, 2020). "Targeting the hydrophobic pocket, N-terminal region, and a novel site of CTDSP1 could provide a new chance to develop cancer-related treatments." (PMID 32397221, 2020). "It is reported that down-regulation of CTDSP1 may promote cancer cell migration and invasion." (PMID 36311195, 2022). "Thus, the regulation of CTDSP1 expression and activity may be related to the development of0 novel strategies for cancer treatment." (PMID 32397221, 2020). "However, there are still many challenges in targeting CTDSP1, such as solving the structural complexity among CTDSPs, finding the unique characteristics of CTDSP1, and looking for novel druggable materials to target CTDSP1 in cancer-related research and development." (PMID 32397221, 2020). "The second complication is that CTDSP1 is implicated in different signaling events, such as neuronal gene silencing, negative regulation of cancer, and cell cycle regulation; hence, nonspecific targeting may impact many different biological activities of CTDSP1." (PMID 32397221, 2020). "This suggests that CTDSP1 can potentially attenuate TWIST1 and antagonize cancer progression." (PMID 32397221, 2020). "CTDSP1 (also known as NIF3, SCP1), negatively regulates cancer cell proliferation." (PMID 31774910, 2019).
CTDSP1 also shares sentences with these, for which no sentence is quoted: gastric cancer (2 papers); amyotrophic lateral sclerosis (1); breast tumors (1); Cerebral ischemia (1); esophageal squamous cell carcinoma (1); liposarcoma (1); lung (1); lung adenocarcinoma (1).